KRAS (KRas proto-oncogene, GTPase)
Diseases named in the same sentence as KRAS in open-access papers (continued):
Sharing a sentence is not in itself a finding about the gene and the disease.
mucinous ovarian tumors (19 papers, 2005 to 2025). "Benign mucinous ovarian tumors frequently harbor mutations in KRAS or Cyclin-dependent kinase inhibitor 2A (CDKN2A)." (PMID 39040449, 2024). "The most common genetic alterations in ovarian mucinous tumors are somatic KRAS mutations, with an incidence of 50% to 68% in borderline and malignant tumors." (PMID 38903727, 2024). "The most frequent genetic alterations in ovarian mucinous tumors are somatic KRAS mutations with a prevalence of 50 to 68% in borderline and malignant tumors generally." (PMID 32290854, 2020). "The activating hotspot mutation G12V in the pivotal oncogene KRAS has been described as the most common single somatic molecular alteration in mucinous ovarian tumors." (PMID 31197119, 2019). "The key role of KRAS mutations in the development of mucinous ovarian tumors is supported also by recent studies." (PMID 29389895, 2018). "Historically, KRAS mutations have been observed in greater than 75 % of mucinous ovarian tumors, although differentiation of MBOT from MC and exclusion of metastatic disease have not consistently been applied in studies of this disease type." (PMID 25986173, 2015). "The pathogenesis of mucinous ovarian tumors is not well understood; however, one consistent finding is the mutation of the KRAS protooncogene (58% in benign mucinous cystadenomas)." (PMID 24891964, 2014). "For example, somatic activating KRAS mutations are found to some extent in most OC subtypes, but are much more common in mucinous ovarian tumours." (PMID 19240718, 2009). "Mutation in KRAS is a key early event for ovarian mucinous tumors." (PMID 31477716, 2019). "Particularly, Lee and coworkers have analyzed a set of mucinous ovarian tumors and have shown a prevalence of KRAS mutations of 0% in normal epithelial ovarian tissue, 57% in mucinous benign tumors, 90% in borderline mucinous neoplasms and 76% in malignant mucinous carcinomas." (PMID 29389895, 2018). "Also, KRAS mutation is frequent in mucinous ovarian tumours, representing another therapeutic option." (PMID 26557882, 2015). "BRAF and KRAS mutations are components of the mitogen-activated protein kinase (MAPK) cascade and KRAS mutations are common in mucinous ovarian tumors and prevalent among 40–50% of MOC cases." (PMID 32556513, 2020).
myeloproliferative neoplasm (19 papers, 2009 to 2025). A clonal hematopoietic stem cell disorder, characterized by proliferation in the bone marrow of one or more of the myeloid (i.e., granulocytic, erythroid, megakaryocytic, and mast cell) lineages. "In patients with NS due to PTPN11 or KRAS mutations associated with myeloproliferative disorder (MPD)/JMML, 3- to 6-monthly CBC with spleen size assessment should be considered starting at birth and continuing until the age of 5." (PMID 35892827, 2022). "KRAS mutations in myeloid cells are associated with myeloproliferative disease in humans and mice." (PMID 30323311, 2019). "When the most common KRAS mutation, G12D, expressed in mouse hematopoietic cells, it leads to a lethal condition known as myeloproliferative neoplasm (MPN)." (PMID 39048945, 2024). "In mice, knock-in of FLT3-ITD or FLT3-TKD, as well as NRAS p.G12D and KRAS p.G12D, induced a myeloproliferative neoplasm, and an AML phenotype was obtained by combination with other variants." (PMID 36499582, 2022). "In these models, whereas loss of ICMT was able to ameliorate KRAS-driven myeloproliferative disease, loss of ICMT accelerated disease progression of KRAS-driven pancreatic neoplasia." (PMID 33579760, 2021). "After ruling out myelodysplastic and other myeloproliferative diseases the patient was finally diagnosed as aCML according to the WHO criteria with mutations in the TET2 gene, the NRAS gene and in the KRAS gene." (PMID 34840744, 2021). "Juvenile myelomonocytic leukaemia (JMML) is an aggressive myeloproliferative neoplasm (MPN) characterized by driver Ras pathway mutations in 85% of cases, including known oncogenic KRAS and NRAS substitutions." (PMID 26854029, 2016).
Pancreatic cysts (19 papers, 2013 to 2025). A cyst of the pancreas that possess a lining of mucous epithelium. "KRAS mutation is observed in precancerous pancreatic duct lesions or pancreatic cyst fluids, including PanINs and IPMNs." (PMID 36673023, 2023). "The reported elements of DNA analysis associated with malignancy were a high amount of pancreatic cyst fluid DNA, high-amplitude mutations, and high amplitude KRAS mutation." (PMID 34884643, 2021). "The guanine-nucleotide-binding protein-alpha stimulating (GNAS) and the Kirsten rat sarcoma viral oncogene homolog (KRAS), an oncogene and proto-oncogene, respectively, have also been identified as commonly mutated in pancreatic cyst fluid." (PMID 32050465, 2020). "Further analysis of GNAS mutations and the addition of GNAS analysis to KRAS mutation findings remain controversial in pancreatic cyst diagnosis." (PMID 32050465, 2020). "The addition of GNAS to pancreatic cyst fluid KRAS testing has been shown to increase the diagnostic accuracy of IPMN identification from 66 to 80.7%, though this does not achieve a statistically superior result to KRAS testing alone (p > 0.05), which has a diagnostic accuracy of 76.6%." (PMID 33673153, 2021). "For example, KRAS mutations, more than 90% of low-grade PanINs harbor the mutations of this, would be representative screening biomarkers in individuals at high risk of pancreatic cysts or apparently normal pancreas." (PMID 33291257, 2020). "As an approach for the PCF detection abbreviated from pancreatic cyst fluid, NGS has recognized KRAS mutations providing 96%–100% specificity and 76%–89% sensitivity for MCNs and BD‐IPMNs." (PMID 39605899, 2024). "Accuracy of the mutation detection was analyzed by PCR amplifying DNA from pancreatic cyst fluid by analyzing 30 samples (15 negative and 15 positive) each for the KRAS and GNAS mutations, followed by sequencing on an ABI 3130 genetic analyzer and two ABI 3730 genetic analyzer instruments." (PMID 38472986, 2024). "Pancreatic cyst fluid can also be analyzed for CEA, amylase, cytology and molecular markers (e.g., KRAS and GNAS)." (PMID 33808853, 2021). "However, KRAS and/or GNAS detection alone in pancreatic cyst fluid has been found to be highly sensitive and specific (100% and 96%, respectively) for the diagnosis of branch duct IPMN." (PMID 36359417, 2022).
brain tumors (18 papers, 2013 to 2025). "KRAS is the most commonly mutated oncogene in human cancer including pancreatic, colon, lung and brain tumors." (PMID 33137185, 2021). "We show that the combination therapy of adagrasib and abemaciclib led to good brain penetration and on-target activity in brain tumors carrying KRAS-G12C and CDKN2A loss and was able to provide survival benefit in an NSCLC brain metastasis model that did not respond to monotherapy." (PMID 40317086, 2025). "Pre-Tx SUVmax of IGs is a potential surrogate marker for KRAS mutation in pediatric brain tumors." (PMID 35130327, 2022). "Although let-7 therapy is not yet established, this review updates the current state of knowledge on the contribution of miRNA let-7 in interaction with KRAS to the oncogenesis of brain tumours." (PMID 38637419, 2024). "In this study, we evaluated zebrafish as a brain tumor model by overexpressing a human version of oncogenic KRAS (KRASG12V)." (PMID 25644510, 2015). "Our study showed that oncogenic KRAS promoted brain tumors in zebrafish, and that tumorigenesis was driven by the activation of the canonical Ras and mTOR pathways." (PMID 25644510, 2015). "Although oncogenic KRAS-induced brain tumors reported in this study resembled astrocytoma morphologically, we cannot exclude the possibility that they are a type of undifferentiated brain tumors, such as primitive neuroectodermal tumors (PNET) which often do not express GFAP." (PMID 25644510, 2015). "Unfortunately, there is currently no effective treatment for primary brain tumors that targets KRAS and has demonstrated good intracranial activity." (PMID 38905571, 2024). "Because our previous study showed that Gal-3 gives rise to mutant KRAS addiction by directly binding to the cell surface receptor integrin αvβ3, we hypothesized that Gal-3 could mediate macropinocytosis allowing mesenchymal GSC to survive in the stressful brain tumor microenvironment." (PMID 34112916, 2021).
dysplasia (18 papers, 2010 to 2025). A usually neoplastic transformation of the cell, associated with altered architectural tissue patterns. "Among 26 lesions located in colitis-affected segments, most displayed SSL-like dysplasia (58%), typically proximal and associated with BRAF mutations, whereas TSA-like dysplasia was more distal and linked to KRAS mutations." (PMID 41303078, 2025). "In our study, although all cases of TSA-like dysplasia were located in the distal colon and showed KRAS mutations, 60% (3/5) were also CIMP-positive." (PMID 36827302, 2023). "This is probably because an activating KRAS mutation is known to occur early in the dysplasia-carcinoma pathway and is therefore likely to be present in virtually every malignant cell." (PMID 36231137, 2022). "BRAF mutations were observed in 75% (3/4) of cases of SSL-like dysplasia in colitis-affected segments and in all SSLs in colitis-unaffected segments, whereas KRAS mutations were observed in all cases of TSA-like dysplasia in colitis-affected segments and in all TSAs in colitis-unaffected segments." (PMID 36827302, 2023). "Conversely, TSA-like dysplasia in colitis-affected segments showed clinical and biological characteristics similar to those of TSAs in colitis-unaffected segments (predominantly in men, in the distal colon, and with KRAS mutations)." (PMID 36827302, 2023). "KRAS mutation occurred more frequently in patients with IBD-CRC compared to IBD patients without dysplasia (RR = 3.09; 95%CI 1.47-6.51, P = 0.003)." (PMID 28077799, 2017). "Across dysplasia samples, multiple oncogenic drivers were seen, including APC, KRAS, and SMAD4 mutations, with no alterations clearly emerging in the transition to carcinoma." (PMID 36611031, 2023).
gynecological cancers (18 papers, 2010 to 2026). "It is important to note that though these trials are open to patients with all solid tumors with the KRAS-G12D mutation, their supporting preclinical data rarely include gynecologic cancer models." (PMID 40896434, 2025). "In gynecological cancers, particularly OCs and ECs, the activation of the KRAS pathway and the presence of KRAS mutations are substantial factors contributing to both de novo and acquired resistance against PI3K pathway inhibitors." (PMID 38920692, 2024). "Similar results were also reported for AZD5363, although exclusive PIK3CA mutations did not correlate with increased response in another study in breast or gynecological cancer patients where concurrent mutations in KRAS, NRAS, HRAS, or BRAF were excluded." (PMID 31835495, 2019). "Recently, targeting multiple modes of PI3K and its compensatory pathways like KRAS and YAP/YEAD has been suggested to benefit KRAS-driven tumors, but further investigation is needed in gynecological cancers." (PMID 38920692, 2024). "Taken together, these findings suggest that targeting KRAS pathway represents an exciting and promising new direction of therapy for gynecological cancers, including endometrial and LGSOC." (PMID 33801965, 2021). "The recent TCGA study of 373 endometrial tumors identified the KRAS and PTEN genes as being mutated in 24.6% and 77% of endometrioid tumors respectively, emphasizing the influence of these mutations in gynecologic cancer pathogenesis." (PMID 25078979, 2014). "Furthermore, upstream/downstream pathway inhibitors (e.g., MEK inhibitors) are under investigation for KRAS-driven gynecologic cancers." (PMID 41597409, 2026). "ERBB2, PIK3CA, ARID1A, and KRAS would be key molecular targets in gynecological cancers." (PMID 38201563, 2023). "This mutational analysis will be very important, given the fact that integrated biomarker-based trials represent the most likely strategy to fully realize the potential therapeutic efficacy of targeted therapy in gynecological cancer with less frequency of alterations in the KRAS pathway." (PMID 33801965, 2021). "Involvement of the KRAS and PTEN pathways has led to the development of several genetically modified preclinical models for type I gynecological cancers." (PMID 25078979, 2014).
head and neck squamous cell carcinoma (18 papers, 2012 to 2025). A squamous cell carcinoma that arises from any of the following anatomic sites: lip and oral cavity, nasal cavity, paranasal sinuses, pharynx, larynx, and salivary glands. "The RAS family of genes is of particular interest in Head and Neck Squamous Cell Carcinoma (HNSCC) because a mechanism for mutation (activation) of KRAS by tobacco carcinogens has been suggested." (PMID 25361007, 2014). "Clinical treatment options for KRAS wild-type EGFR in head and neck squamous cell carcinoma (HNSCC) and metastatic colorectal cancer (mCRC), encompass monoclonal antibodies (mAbs) cetuximab and panitumumab." (PMID 27602494, 2016). "In addition to point mutations and stimulation with receptor ligands, exposure to a clinically relevant dose of IR rapidly activates K-Ras in KRAS wild-type head and neck squamous cell carcinoma FaDu cells." (PMID 36313934, 2023).
acute lymphoblastic leukemia (17 papers, 2011 to 2026). Leukemia with an acute onset, characterized by the presence of lymphoblasts in the bone marrow and the peripheral blood. "NRAS or KRAS mutations detected in approximately 20–40% of myeloid malignancies and 10–15% of acute lymphoblastic leukemia cases." (PMID 39048945, 2024). "Studies of infant and paediatric patients with MLL-AF4+ B cell precursor acute lymphoblastic leukaemia (BCP-ALL) have reported mutations in KRAS and NRAS with incidences ranging from 25 to 50%." (PMID 27698462, 2016). "KRAS mutations predominantly occur at critical amino acid residues (G12, G13, Q61, and A146) and are frequently implicated in various hematologic malignancies, including acute lymphoblastic leukemia (ALL), myelodysplastic syndromes (MDS), juvenile myelomonocytic leukemia (JMML), and AML." (PMID 40951356, 2025). "In pediatric B-cell precursor acute lymphoblastic leukemia (BCP-ALL), KRAS is mutated in approximately 44% of cases and is linked to relapse as well as chemotherapy resistance." (PMID 33801965, 2021). "CBP can directly acetylate KRAS, and acetylated KRAS inhibits RAS/RAF/MEK/ERK signal transduction in acute lymphoblastic leukaemia cells with Ras pathway mutations." (PMID 39778006, 2025). "One of the related studies of IL-1β is with acute lymphoblastic leukemia, in which IL-1β is known to induce NF-κB activation; more importantly, in KRAS mutant cancer cells, it leads to drug resistance and increased cancer progression." (PMID 36840009, 2023). "Mutations in RAS pathway proteins (e.g., KRAS, NRAS, FLT3, PTPN11, and NF1) are highly prevalent in acute lymphoblastic leukemia (ALL), with such mutations occurring in 40%–50% of pediatric B cell ALL cases." (PMID 35243242, 2022). "In acute lymphoblastic leukemia, KRAS (Kirsten rat sarcoma viral oncogene homolog) G12D mutation is responsible for the binding of cAMP response element binding (CREB) on IL1B promoter and increases the expression of IL-1β in these cells." (PMID 32635472, 2020).
ductal adenocarcinoma (17 papers, 2003 to 2025). "While KRAS mutations are commonly found in ductal adenocarcinomas, they are exceedingly rare in ACCs." (PMID 26137463, 2015). "Analysis showed that KRAS mutations were associated with reduced patient survival in both malignant exocrine and ductal adenocarcinomas (PDAC)." (PMID 23565280, 2013). "However, approximately 90% of PAAD are ductal adenocarcinomas with KRAS mutations as the primary driver, which are typically characterized by fibrous tissue hyperplasia and reduced vascularity, which in turn leads to immunosuppression and resistance to chemotherapy and immunotherapy." (PMID 37822927, 2023). "However, the most common molecular alterations found in ductal adenocarcinoma (KRAS), cystic neoplasms (GNAS and RNF43), and NENs (MEN1, DAXX, and ATRX) are rarely found in ACC." (PMID 41120769, 2025). "Four of seven patients with KRAS-mutant MCP died within 1 year; these outcomes are similar to those of patients with advanced typical ductal adenocarcinomas." (PMID 30043132, 2018).